HINT1 (histidine triad nucleotide binding protein 1)
Diseases named in the same sentence as HINT1 in open-access papers (continued):
Sharing a sentence is not in itself a finding about the gene and the disease.
substance abuse (1 paper, 2024). The use of a drug for a reason other than which it was intended or in a manner or in quantities other than directed. "HINT1 was identified for the stratum pyramidale in females in a study analysing hippocampal neuroanatomy correlating with spatial learning ability in mice, pointing to its role in neuroplasticity, another factor influencing and influenced by substance abuse." (PMID 38279213, 2024).
tumor (34 papers, 2013 to 2025). "HINT1 encoded a protein that hydrolyzes purine nucleotide phosphoramidate substrates that play a role in tumor suppression." (PMID 40453362, 2024). "The deletion of Hint1 has been shown to increase susceptibility to carcinogenesis in mice, further supporting its tumor suppressor role." (PMID 38068718, 2023). "In contrast, HINT1 encodes a protein that hydrolyses purine nucleotide phosphoramidate substrates and is believed to be act mainly as a tumour suppressor in multiple cancer types." (PMID 36315425, 2022). "Histidine triad nucleotide-binding protein 1 (Hint1) is a tumor suppressor often downregulated in association with the development of cancer." (PMID 35991893, 2022). "The function of HINT1 as a tumor suppressor is supported by observations that a deficiency of HINT1 in mice led to increased susceptibility to both spontaneous and carcinogen-induced tumor formation." (PMID 32636443, 2020). "The deficiency of HINT1 in mice results in increased susceptibility to both spontaneous and carcinogen-induced tumor formation." (PMID 31604935, 2019). "Histidine triad nucleotide‐binding protein 1 (HINT1) is regarded as a haplo‐insufficient tumor suppressor and is closely associated with diverse neuropsychiatric diseases." (PMID 29075577, 2017). "However, the effects of Hint1 deficiency on the ceRNA regulatory network of tumor cells need to be clarified." (PMID 35241097, 2022). "Besides, both Hint1−/− and Hint1+/− mice exhibit an elevated rate of spontaneous tumor development, and enhanced susceptibility to tumor induction by 7,12-dimethylbenzanthracene." (PMID 34177485, 2021). "HINT1, a tumor suppressor, is involved in various functions such as cell signaling and gene expression." (PMID 40695554, 2025). "Many studies have suggested that HINT1 inhibits tumor initiation and progression through transcriptional regulation." (PMID 38485947, 2024). "This indicates the diversity of hub lncRNAs in the regulation of the tumor malignant phenotype, and also confirms the significant role of the Hint1-related ceRNA network in malignant tumors." (PMID 35241097, 2022). "Histidine triad nucleotide-binding protein 1 (HINT1) is a tumor suppressor, which belongs to the triple histidine superfamily." (PMID 35241097, 2022). "Hint1 exerts its tumor suppressor activity by binding to transcription factors, such as MITF and β-catenin, and its suppressive function is in turn regulated by an acetylation-dependent mechanism." (PMID 33671384, 2021). "They found that the deacetylation of HINT1 by SIRT1 promotes the capacity of HINT1 to bind to transcription factors, thereby enhancing its tumor-suppressing function." (PMID 32636443, 2020). "Next, we performed immunohistochemistry staining on 110 samples from Peking University People's Hospital to evaluate the expression of HINT1 in tumor tissues." (PMID 33123275, 2020). "Taken together, the results of this study indicate that the tumor-suppressive function of HINT1 can be regulated by an acetylation-dependent mechanism involving CBP and SIRT1." (PMID 32636443, 2020). "This suggests the possibility that dysfunction of HINT1-mediated tumor-suppressive activity can be governed by mechanisms other than its expression level in cancers." (PMID 32636443, 2020). "HINT1 is known to bind to and inhibit several tumor-promoting transcription factors, but it is unclear how this process is regulated." (PMID 32636443, 2020). "The expression of HINT1 in patients with different stages of tumor varies and is related to the prognosis, rendering it to be a potential target for drug treatment." (PMID 33123275, 2020).
tumor (continued). "In this context, HINT1 is recruited by the DNA damage response, triggers apoptosis, exhibits tumor-suppressive activity, and inhibits proliferation in human gastric and colon cancer cells." (PMID 31088288, 2019). "It is of an interest that HINT1 has been assigned a variety of roles including apoptotic, transcriptional, and tumor suppressor activities." (PMID 31777173, 2019). "The known functions of HINT1, such as tumor suppression, nucleoside transferase, and hydrolase functions, are only a tiny fraction of the whole picture." (PMID 29214080, 2017). "Accumulating evidence indicates that HINT1 plays a role as a haploinsufficient tumor suppressor in multiple malignant diseases, but little is known about the mechanism." (PMID 29214080, 2017). "HINT1 was originally identified as a tumor suppressor and an inhibitor of PKC." (PMID 40695554, 2025). "Furthermore, HINT1 is also known to regulate transcription factors involved in tumor progression and apoptosis." (PMID 39596683, 2024). "HINT1 is regarded as a tumor suppressor in various malignancies." (PMID 38485947, 2024). "Additionally, Hint1 has been identified as a tumor suppressor by regulating multiple molecular mechanisms, such as gene transcription, apoptosis, and cell cycle control." (PMID 38068718, 2023). "In addition, histidine triad nucleotide-binding protein 1 (HINT1), a novel tumor suppressor stabilizes IκBα protein levels by targeting β-TrCP." (PMID 35273593, 2022). "HINT1 protein can affect the transcription of downstream target genes by interacting with a variety of transcription factors, thereby regulating the proliferation, apoptosis, invasion, and migration of tumor cells." (PMID 35241097, 2022). "It has been reported that Hint1 can play a role in transcription regulation that could affect tumorigenesis signaling pathways, and it has been observed that Hint1 protein can act as tumor-suppressor." (PMID 33671384, 2021). "However, Hint1 reportedly functions as a tumor suppressor by activating ATM and the subsequent DDR20." (PMID 33953175, 2021). "In fact, overexpression of HINT1 2KR, a deacetylation mimetic HINT1 mutant, caused a significant decrease in tumor formation, further confirming that reversible acetylation of HINT1 might have an important role in HINT1-mediated tumor-suppressive activity." (PMID 32636443, 2020). "Thus, this study reveals an acetylation-dependent regulatory mechanism that governs the tumor-suppressive function of HINT1." (PMID 32636443, 2020). "There is accumulating evidence that HINT1 might be a novel tumor suppressor, with action unrelated to its enzymatic activity as a nucleotide hydrolase and/or its transferase activity." (PMID 32636443, 2020). "Based on these reports, this study sought to determine whether SIRT1 can regulate the tumor-inhibiting activity of HINT1 through deacetylation in colon and melanoma cancer cells." (PMID 32636443, 2020). "Indeed, stable expression of the HINT1 2KR mutant led to a much smaller tumor size than the control or HINT1 WT." (PMID 32636443, 2020). "As a result, the tumor-suppressive function of HINT1 is increased." (PMID 32636443, 2020). "Taken together, these results indicate that reversible acetylation of HINT1 by CBP and SIRT1 may be a major mechanism for regulation of HINT1 tumor-suppressive activity." (PMID 32636443, 2020). "A recent study showed that the HINT1-mediated tumor-suppressive function might be modulated by reversible acetylation." (PMID 32636443, 2020). "In addition to its inhibitory effect on tumor formation, HINT1 also plays a role in many pathophysiological states 20-23." (PMID 33123275, 2020). "Subsequently, we validated the target gene of SNP rs1010208 in the specimens from Peking University People's Hospital and found that HINT1 not only presented a cis-eQTL correlation with SNPrs1010208 but also a statistically significant difference in the expression between tumor and adjacent tissues." (PMID 33123275, 2020).
tumor (continued). "These interactions may also influence events in the nucleus, where HINT1 exerts its anti-tumor activity and interacts with transcription factors." (PMID 31249525, 2019). "HINT1, as a haploinsufficient tumor suppressor, could trigger the extrinsic apoptosis pathway to inhibit tumoral growth." (PMID 29937721, 2018). "HINT1 was originally considered a tumor suppressor, and may inhibit tumor growth by initiating relevant apoptotic pathways." (PMID 29937721, 2018). "Moreover, elevated expression and unfavourable prognostic performance of HINT1 was found in MM, and further cellular assays shows that HINT1 silencing induced cell cycle arrest, implying its oncogenic role in MM, compared with its tumour-suppressing role in solid cancers." (PMID 36315425, 2022). "Moreover, higher levels of histidine triad nucleotide-binding protein 1 (HINT1) in Ag 20 nm treated cells were also observed that is involved in apoptotic processes and may also have tumor suppressor functions." (PMID 26888332, 2016). "Histidine triad nucleotide binding protein 1 was first supposed to be PKC inhibitor 1, and then found to be a haplo-insufficient tumor suppressor protein." (PMID 34177485, 2021). "S100A9, which we found up-regulated in pT1-HG biopsies, was identified as a protein associated with iNOS activity, and it is also involved in the regulation of signal transduction, such as SOD2, APOA1, HSP90, HSPA5, HINT1, MYDGF, and SerpinB3, and in immunomodulation in tumor microenvironments." (PMID 41441336, 2025). "When HINT1 is overexpressed in SW480 and McF-7 tumor cells, it leads to a decrease in Bcl-2 levels, an increase in Bax levels, and elevated expression of caspase-9, caspase-8, and caspase-3, ultimately resulting in the induction of apoptosis in tumor cells." (PMID 38068718, 2023). "No relation was found between Hint1 expression and tumor size (p = 0:822), gender (p = 0.560), hormonal type (p = 0.953), and recurrence (p = 0.295)." (PMID 33671384, 2021). "The present data reveal that CBP- and SIRT1-driven reversible acetylation of HINT1 at both K21 and K30 affects the capacity of HINT1 to bind to β-catenin or MITF, which, in turn, can influence its tumor-suppressive activity in cancer cell lines and in an in vivo xenograft mouse model." (PMID 32636443, 2020). "Importantly, the tumor suppressor functions of HINT1 appear to be independent of its enzymatic activity, as a mutant HINT1 (H112N) defective in AMP-NH2 hydrolyzing activity was not impaired for induction of apoptosis." (PMID 31604935, 2019). "For example, PTEN, RBL1, CDKN2AIP, RNASET2A, HINT1, and PARP12 are well-known tumor suppressors and were downregulated or absent in the CT26/SCID tumors." (PMID 38672200, 2024). "Furthermore, a recent study showed that HINT1 is subjected to K21 acetylation and Y109 in activated mast cells, together with Ap4A-mediated HINT1 release from MITF16, suggesting that posttranslational modifications of HINT1 could be a key mechanism for HINT1’s tumor-suppressive role." (PMID 32636443, 2020). "Finally, these genes were overlapped with the upregulated DEGs from the two GSE9782 datasets, resulting in 7 tumor stemness-related genes, including NONO, CBX3, SLC25A3, PTPRG, NPM1, HINT1, HNRNPA1." (PMID 41050668, 2025).
cancer (16 papers, 2013 to 2025). A tumor composed of atypical neoplastic, often pleomorphic cells that invade other tissues. "However, currently, little clinical relevance of HINT1 expression or mutation in several human cancers has been reported." (PMID 32636443, 2020). "Alterations in the levels of some proteins in the COS–GA group, such as HSPA9, HIST2H2BF, keratin 18, HINT1, and vimentin, were proposed as anti-cancer mechanisms in this study." (PMID 37371778, 2023). "HINT1 protein can regulate the transcription of a variety of cancer-related genes by directly binding a variety of transcription factors, including AP1, MITF, and USF2, thus affecting the carcinogenesis and progression of tumors." (PMID 35241097, 2022). "To explore the impact of HINT1 on sensitivity to NUC-7738, we grouped cancer cell lines into low, medium, and high according to their relative HINT1 mRNA expression levels and treated them with NUC-7738 or 3′-dA." (PMID 34497073, 2021). "Currently, studies are focusing on the clinical relevance of HINT1 expression in several human specific cancers." (PMID 29214080, 2017). "Then, combined with TCGA (The Cancer Genome Atlas) database, a DElncRNAs diagnosis model was constructed, and hub DElncRNAs that may be regulated by Hint1 were screened out." (PMID 35241097, 2022). "The role of Hint1 in cancer migration and invasion has been analyzed." (PMID 33671384, 2021). "Hint1 is implicated in transcription regulation and growth control, and the HIT family of proteins, to which Hint1 belongs, is often found inactive in many carcinomas." (PMID 28884116, 2017). "Considering the role of Hint1 in the regulation of transcription, we speculated that it may indirectly regulate the ceRNA network by affecting the transcription of lncRNAs, thus influencing the progress of malignant tumors." (PMID 35241097, 2022). "Thus, the results suggest that the role of CBP, which promotes tumorigenesis by activating Wnt signaling in cancer, may be accomplished by upregulating HINT1 and β-catenin acetylation." (PMID 32636443, 2020). "Anti-cancer-activity-related proteins were altered, including CLTA, HSPA9, HIST2H2BF, KRT18, HINT1, DSP, and VIM." (PMID 37371778, 2023). "In searching for the unknown activity of HINT1, we noticed that a series of HINT1-interacting proteins, such as transcription factors and RGS-Rz proteins, which have been implicated in multiple human cancers, are regulated by covalent conjugation of the small ubiquitin-like modifier (SUMO)." (PMID 31088288, 2019). "However, six proteins influenced cancer cell survival in the COS–GA group in previous studies, with downregulated HSPA9 and HIST2H2BF and upregulated KRT18, HINT1, DSP, and VIM proteins." (PMID 37371778, 2023). "Importantly, HINT1 protein is present across numerous cancer types and its depletion was not dose-limiting, implying that even low levels of HINT1 are sufficient for NUC-7738 activation." (PMID 34497073, 2021). "In addition, the analysis also shows that acetylation of HINT1 by CBP promotes the release of β-catenin from the HINT1-β-catenin complex to enhance the transcriptional activity of β-catenin, which in turn boosts oncogenic features in cancer." (PMID 32636443, 2020). "Triple-labeled immunofluorescence (BTF3, HINT1 and NDRG1) in tissue array showed a significant (p<0.02) change in co-localization coefficients for BTF3 and NDRG1 co-expression in biochemical relapse vs non-relapse cancer epithelium." (PMID 24386364, 2013).
psychiatric disorder (3 papers, 2017 to 2026). A disorder characterized by behavioral and/or psychological abnormalities, often accompanied by physical symptoms. "In addition, psychiatric and cognitive features were not systematically assessed in patients with HINT1 variants, representing another limitation, given emerging evidence suggesting a potential role of HINT1 in psychiatric disorders." (PMID 41549766, 2026).
cardiovascular diseases (2 papers, 2025). "Studies suggest that HINT2 mitigates pressure‐overload‐induced cardiac remodeling by affecting the activity and assembly of mitochondrial complex I. However, research on HINT3, a family member of HINT1 and HINT2, is scarce, especially in the context of cardiovascular diseases." (PMID 40755357, 2025).
nervous system disease (2 papers, 2015 to 2022). "The nervous system disease class consists of proteins APP, DYNC1H1, DYNC1I2, HINT1, LSM2, RNF11, SNCA in between 30% and 40% association." (PMID 34918006, 2022).
infection (1 paper, 2013). The state of being infected such as from the introduction of a foreign agent such as serum, vaccine, antigenic substance or organism. "Infection of HINT1-/- neurons with 1 μL/well of the lentiviral particles also restored WIN55,212-2-mediated neuroprotection against NMDA toxicity." (PMID 24093505, 2013). "Furthermore, infection of HINT1-/- neurons with HINT1 lentiviral particles increased HINT1 expression, which resulted in the co-precipitation of CNR1 with the NR1 subunits." (PMID 24093505, 2013).
peripheral neuropathy (1 paper, 2021). A disorder affecting the peripheral nervous system. "In a cohort of 748 Norwegian patients with suspected peripheral neuropathy, we identified two seemingly unrelated individuals, compound heterozygous for a new variant (c.284G > A, p.Arg95Gln) and the most common pathogenic founder variant (c.110G > C, p.Arg37Pro) in the HINT1 gene." (PMID 33663550, 2021).
HINT1 also shares sentences with these, for which no sentence is quoted: breast carcinoma (3 papers); psychosis (3); Charcot-Marie-Tooth (CMT) disease (2); colorectal cancer (2); distal motor neuropathy (2); Ewing sarcoma (2); neurodegenerative disease (2); age (1); anaphylaxis (1); asthma (1); Charcot-Marie-Tooth neuropathy (1); chronic hepatitis (1); Cirrhosis (1); colorectal adenocarcinoma (1); cortical dysplasia (1); Crohn disease (1); dementia (1); Dependence (1); epilepsy (1); Fanconi anemia complementation group M (1); Fronto-temporal dementia (1); gastric tumors (1); generalized anxiety disorder (1); glycogen storage disease X (1); Lissencephaly (1); lung adenocarcinoma (1); lung carcinoma (1); malignant mesothelioma (1); myasthenia gravis (1); Myokymia (1).
A further 5 diseases each share a sentence with HINT1 in 1 paper.